CCL17 (C-C motif chemokine ligand 17)
Diseases named in the same sentence as CCL17 in open-access papers (continued):
Sharing a sentence is not in itself a finding about the gene and the disease.
tumor (continued). "The frequency of myeloid-derived suppressor cells (MDSCs), however, was significantly decreased in tumors of CCL17 TG mice, suggesting that decreased MDSCs might promote tumor immunity." (PMID 33670758, 2021). "In one way, CCL17 increases both Tregs and Th2 cells, upregulating tumor formation." (PMID 33670758, 2021). "In the present study, tumor formation was enhanced in CCL17 TG mice." (PMID 33670758, 2021). "Depletion of Tregs significantly decreased tumor size both in CCL17 TG mice and WT mice." (PMID 33670758, 2021). "The combination treatment caused increased secretion of CCL2, CCL21, CXCL1, CXCL2, CXCL5, CXCL9 and CXCL16, whereas the levels of CCL11, CCL17, CCL19, CCL22, CCL25, CCL27 and CX3CL1, which are associated with protumourigenic effects, were decreased in the tumours." (PMID 33014356, 2020). "This was due to secretion by CD4+ T cells of pro-tumor Th2 cytokines (i.e., mainly IL-10 and IL-13), possibly with activation of CD4+ NKT and myeloid suppressive cells, and tumor-derived CCL17 that in turn recruited Tregs already described to have a pro-metastatic role in breast cancer." (PMID 33042121, 2020). "Additionally, intratumoural IFN-α gene delivery reduced the trafficking of Tregs to the tumour through the downregulation of tumour CCL17 expression." (PMID 32680511, 2020). "Therefore, in mouse HCC models, intratumoral injection of antibodies targeting CCL2 and CCL17 reduces the migration activity of macrophages and Treg cells, and delays tumor growth." (PMID 33224886, 2020). "We also show changes in DCs, where Siah2 loss increased expression of the IFNγ-induced chemokine Cxcl9, which recruits effector T cells to a tumor site, and concomitantly decreased expression of Ccl17 and Ccl22, chemokines that contribute to recruitment of Tregs to tumors." (PMID 31911617, 2020). "Cells exposed to proliferating thyrocytes or Nthy CM had an M0-like phenotype, while cells exposed to senescent thyrocytes or tumor cells CM (STh- and TuC-Macro) showed M2-like polarization (low MHC II, high CD206 or CD163 and high CCL17 production) and displayed tumor promoting activity." (PMID 31113465, 2019). "Moreover, CCL17-expressing macrophages and dendritic cells accumulated in the tumors indicating the establishment of a tumor-promoting immunosuppressive environment." (PMID 31681563, 2019). "Thus, the tumor microenvironment which is established in colon and SI tumors of Apc1638N/+ mice favors CCL17 expression in TAMs and DCs." (PMID 31681563, 2019). "The predominant chemokine receptor on human Treg is CCR4, the receptor for the chemokines CCL17 and CCL22, which are produced by tumor cells, tumor- associated macrophages and dendritic cells, as well as by effector T cells (Teff) in the setting of an inflammatory anti-tumor response." (PMID 30400822, 2018). "The subset of genes upregulated in lungs of both tumor free and metastatic Ikkβ-deficient animals comprised Tnfa, Ccl5, Ccl17, Ccl22, Cxcl1 and Csf2, although not all changes reached significance." (PMID 29682184, 2018). "The increased levels of CCL17 in the brain could chemo-attract tumor cells expressing the corresponding CCR4 receptor to the brain." (PMID 28415693, 2017). "CCL17 was considered to attract CCR4+ Treg cells to the tumor." (PMID 28178948, 2017). "Further researches were required to investigate the roles of CCL17 in ccRCC tumor cells." (PMID 28178948, 2017). "CCL17 created a favorable environment where tumor cells could escape from host immune responses in some type of cancers." (PMID 28178948, 2017). "Regarding the mechanisms involved in the increased recruitment of macrophages into ARF−/− tumor xenografts, upregulation of chemokines and growth factors including CCL-17, CCL-22, CCL-5 and TGF-β might be critical." (PMID 27572316, 2016).
tumor (continued). "Production of CCL17, CCL1, chemokine (C-X-C motif) ligand-13 (CXCL13) and CXCL8 (IL-8) has been shown to be associated with the activation program for M2 tumor associated macrophage (TAM), and is parts of mononuclear phagocyte-mediated regulatory circuits of innate and adaptive immunity." (PMID 26172457, 2015). "Furthermore, IL-17A produced by MDSCs recruits Treg cells at tumor sites via up-regulation of chemokines CCL17 and CCL22 and enhances their suppressor function via up-regulation of CD39 and CD73." (PMID 23372655, 2013). "The tumor-associated mucosa had a decrease in MAdCAM-1+ and increase in PNAd+ blood vessels compared to in the unaffected mucosa and also increased production of the CCR4 ligand CCL17." (PMID 22319577, 2012). "In the immunogenic model RLS40, DNase I had anti-tumor, antimetastatic, and immunostimulatory effects and significantly modified the neutrophil profile by decreasing the expression of the immunosuppressive markers (Il10, Ccl17) and increasing the expression of the anti-tumor markers (PD-L1, FAS)." (PMID 40867260, 2025). "Moreover, whether M2-like macrophages-derived CCL17 could exert its tumor-promoting effects via CCR4-mediated ERK/PD‐L1 signaling was thoroughly elucidated." (PMID 39473097, 2025). "Additionally, STING agonist may confer an antitumor effect by suppressing CCL17 expression or CCL17-expressing cells and thereby suppressing Treg migration into the tumor microenvironment (TME)." (PMID 39113096, 2024). "Typically, macrophages infiltrated in tumors, named tumor-associated macrophages (TAM), shows M2-polarization characteristics and promote tumor malignant progression by secreting a variety of cytokines (e.g., TGFB1 and HMGB1) and chemokines (e.g., CCL17 and CXCL7)." (PMID 38576043, 2024). "Finally, to establish a link between CCL17 in rrDLBCL tumor cells and CD4+ T-cell infiltration, CCL17 mRNA expression was compared between CD4High and CD4Low samples, and there was a striking increase in tumor cell CCL17 mRNA expression in samples with CD4High staining." (PMID 38285120, 2024). "LMP1 and/or other viral proteins may lead to the indirect production of CCL17/22 in EBV+ tumors via recruitment of infiltrating cells such as dendritic cells followed by tumor-intrinsic CCL17/22 expression in response to the activity of these infiltrating immune cells." (PMID 35025968, 2022). "Thus, tumor growth was enhanced where CCL17 was highly expressed." (PMID 33670758, 2021). "Therefore, DON treatment may promote the expression of the hallmarks of tumour formation given its effect on pyroptosis-related genes and CCL17 expression." (PMID 34440667, 2021). "Thus, MDSCs were decreased in the tumor microenvironment in CCL17 TG mice, which might function as a negative regulator preventing severe tumor immune dysfunction." (PMID 33670758, 2021). "Thus, CCL17 attenuates tumor immunity by increasing Tregs and Th2 cells, while it decreases MDSCs through reductions in CXCL17, which may work as a “safety-net” to reduce the risk of malignant tumors in the Th2-dominant environment." (PMID 33670758, 2021). "Besides CAFs, tumor-associated macrophages (TAMs), as myeloid derived suppressor cells, contribute to an immunosuppressive microenvironment and support tumor growth as they are a source of immunosuppressive cytokines (e.g., CCL17, CCL18 and CCL22) and tumor promoting growth factors (VEGF-A, TNF-α)." (PMID 34064974, 2021). "Moreover, CCL17 levels positively promoted tumor growth in human PAs." (PMID 33664865, 2021). "We next determined if depletion of Tregs could change tumor formation in CCL17 TG mice." (PMID 33670758, 2021). "Thus, naturally occurring Foxp3+ T-regs may be induced to migrate from the peripheral blood to the tumor sites by the chemokines CCL17, CCL22, and CCL5 and then increase in number by tumor-related factors to create a favorable environment for tumor growth." (PMID 29772686, 2018).
tumor (continued). "Circulating tumor DNA (ctDNA) and soluble mediators such as thymus and activation-regulated chemokine (TARC/CCL17) provide measurable evidence of systemic disease activity and enable dynamic monitoring of tumor burden." (PMID 42279396, 2026). "This review compiles current knowledge on the significance of lesser-known chemokines in MM tumor processes, including CXCL13, CCR2 ligands (CCL2 [MCP-1], CCL7 [MCP-3]), CCL4, CCL5 (RANTES), CCL17, CCL20, CCL27, CCL28, and CX3CL1 (fractalkine)." (PMID 41749925, 2026). "In pathophysiological conditions, such as cancer metastasis, the CCL17/CCL22–CXCR4 axis enhances tumour cell migration and invasion by modulating the tumour microenvironment." (PMID 41291326, 2025). "CCL17 and CCL22 promote the homing of Tregs to the lungs, whereas CCL2 is required for the recruitment of Tregs to tumor sites." (PMID 39740041, 2025). "Tumor cells and stromal cells recruit Tregs to the tumor site primarily by secreting chemokines such as CCL22, CCL17 (binding to CCR4 on Tregs), and CCL28 (binding to CCR10)." (PMID 40698080, 2025). "In vitro migration assays further demonstrate that CCL17, CCL20, and CCL22 exert chemotactic effects on tumor-derived Th17 cells." (PMID 40134607, 2025). "It has been hypothesized that CCL17 expression by Langerhans cells, endothelial cells, and fibroblasts facilitates the recruitment of malignant T cells and Th2-polarized cells to the skin, contributing to the Th2-skewed tumor microenvironment typical of advanced CTCL." (PMID 40861461, 2025). "Previous studies have shown that CCR4, binding with CCL17/CCL22, can induce Treg cell enrichment within the tumour microenvironment (TME)." (PMID 40000397, 2025). "Co-expression of CCR4 improved the homing ability of anti-CD30 CAR-T cells to Hodgkin tumor sites by enhancing their migration toward CCR4 ligands CCL17 and CCL22, which are highly expressed in the tumor microenvironment." (PMID 41181132, 2025). "This study seeks to investigate the clinical significance of CCR4, CCL17, CD73, and HHLA2 in HCC, exploring their interconnectedness within the tumor immune microenvironment." (PMID 38914802, 2024). "This investigation aims to delineate the roles of CCL17 and CCR4 in modulating the tumor’s immune landscape, assessing their potential as therapeutic interventions and prognostic markers in HCC." (PMID 38914802, 2024). "In this study, we established a correlation between high expression levels of CCR4, CCL17, CD73, and HHLA2 in tumor tissues and the poor prognosis in HCC patients." (PMID 38914802, 2024). "CCL17 expression in M2 macrophages can induce EMT and activate the Wnt/β-catenin signaling pathway in tumor cells (Liu R-X." (PMID 38957393, 2024). "Intriguingly, CCL17 and CCR4 were also found to be widely expressed in tumor stroma, hinting at a subtype of stromal cells, mainly immune cells, expressing these two molecules." (PMID 38914802, 2024). "Cytokines such as CCL17 and CCL15 expressed from TAMs attract regulatory T cells (T regs) into the tumor stroma, whereas IL-10 and TGF-β suppress T-cell-mediated anti-tumor immune responses." (PMID 38672714, 2024). "Chemokines chemokine C-C motif ligand (CCL) 9 (CCL9), CCL17, CCL20, CXCL5, CXCL9, and CXCL10 secreted by hepatocytes regulated tumor progression by acting on CD8+ T cells." (PMID 39346534, 2024). "Tregs are recruited by tumor tissues in the TME through a variety of chemokines, leading to Treg enrichment locally in the tumor (CCL17/22-CCR4, CCL5-CCR5, CCL1-CCR8, CCL28-CCR10 and CXCL9/10/11-CXCR3, etc.)." (PMID 39329710, 2024). "Chemokines secreted by macrophages, like CCL17 and CCL22, attract Tregs to the tumor area, enhancing Treg infiltration within the TME and further sustaining the tumor’s ability to evade immune detection." (PMID 39290699, 2024). "CCR4 induces chemotaxis in response to its target chemokines, CCL17 and CCL22, which are often upregulated in tumor microenvironments." (PMID 38254876, 2024).
tumor (continued). "Recent findings implicate the chemokine ligand 17 (CCL17) and its receptor CCR4 as pivotal players in the tumor microenvironment (TME) of various cancers." (PMID 38914802, 2024). "CCL17 has been shown to specifically attract CCR4+ Tregs, and blocking Treg migration with a CCR4 antagonist has the potential in promoting anti‐tumour immunity." (PMID 39031979, 2024). "This property has been applied in tumour therapy by targeting CCR4, the ligand of CCL17 to reduce Treg suppression." (PMID 39031979, 2024). "CCL17 expression in M2 macrophages can activate Wnt/β-catenin signaling and promote EMT of tumor cells, while tumor cells in turn activate TAMs through the TLR4/TRIF/NF-κB signaling pathway and increase IL-1β production mediated by HIF1α to trigger EMT." (PMID 38957393, 2024). "Meanwhile, macrophages can promote tumor invasion and metastasis through secretion of various cytokines (e.g., TGF-β, IL-10, arginase 1) and chemokines (e.g., CCL5, CCL17, CCL18, CCL22)." (PMID 38637499, 2024). "The decrease in the percentage of M2 TAMs visible by cytometry was also confirmed by the decrease in CCL17 and CCL22 mRNA (M2 macrophages markers), as well as CXCR2 mRNA in the tumor." (PMID 38504270, 2024). "Next, we further explored the relationship between CCL17, CCR4, and tumor angiogenesis in human HCC tissues." (PMID 38914802, 2024). "The most relevant finding of our study is the lower tumor cell content and the low levels of CCL17/TARC expression in HLA‐I+ HL." (PMID 38836098, 2024). "CCL17 (TARC) is highly secreted by Reed–Sternberg cells and is involved in recruiting CD4 + T-cells to the tumor site where they suppress local immune responses by inhibiting the function of cytotoxic CD8+ T-cells." (PMID 39769007, 2024). "Mechanistically, TAM-secreted C-C motif chemokine ligand 17 (CCL17) and CCL22, via membrane receptor CCR4, activated the PI3K/AKT pathway in CRC tumor cells." (PMID 37658050, 2023). "As compared to the control group, the expression of MR, ARG-1 and CCL17 were also upregulated, indicating that DCA can promote the polarization of M2 macrophages and in turn lead to tumor cell proliferation and intestinal tumorigenesis." (PMID 37943609, 2023). "As CCR4 is the shared receptor for both CCL17 and CCL22 and is reported to be overexpressed in tumor cells, we next examined its expression on the membrane of CRC cells and reproducibly detected strong signals in the isolated membrane fractions." (PMID 37658050, 2023). "CCL17, CCL19, and CCL22 have been shown to mediate DC trafficking between the tumor and draining lymph nodes while promoting the activation of tumor-specific T cells." (PMID 37532692, 2023). "Accordingly, inhibiting transcriptional regulators of CCL2/CCL17, like p38 and AKT, significantly improved tumor sensitivity to sorafenib." (PMID 38139412, 2023). "CXCL1 induces the recruitment of neutrophils into the HCC tumor niche; these cells secrete CCL2 and C-C motif ligand 17 (CCL17, thymus and activation-regulated chemokine (TARC)), which induce the recruitment of monocytes and Treg, respectively." (PMID 37408240, 2023). "The TAMs are primarily present in the tumor stroma, and POSTN encourages CD163+ macrophages to release various cytokines, including Treg-related chemokines (CCL17 and CCL22)." (PMID 37525217, 2023). "Tregs are a crucial therapeutic target in the TME, they can be recruited to the TME by macrophages and tumor-derived factors such as CXCL12, CCL17 CCL22 and CCL1, thus suppressing the activation of T cells." (PMID 37656220, 2023). "Some information shows that TAM can not only promote angiogenesis and support tumor growth by secreting cytokines such as TGF-β, but also recruit T cells by secreting CCL17 and CCL22." (PMID 36969873, 2023). "On the other hand, NKT cells can stimulate the secretion of C-C motif chemokine ligand 17 (CCL17) by activating CD8α+ DC cells and attracting CD8+ cells to the tumor site." (PMID 37158883, 2023).
tumor (continued). "Treg cells are mainly recruited to the tumor microenvironment by chemokines such as CCL1, CCL17, CCL22, CCL28, CXCL9, CXCL10, and CXCL11." (PMID 37686093, 2023). "TAMEMs highly express mitogenic and angiogenic factors (e.g., VEGF, PDGF, and Ang) and immunosuppressive cytokines (e.g., IL‐10, CCL17, and TGF‐β), comparable to those in TAMs, which are typical features of the latter in promoting tumor development." (PMID 36541165, 2023). "We found that after co-culturing with macrophages, the polarization ratio of M2-type macrophages increased significantly, and the levels of tumor-promoting cytokines TGF-β1, CCL17, and M-CSF were significantly increased." (PMID 37671167, 2023). "Here, we show that out of a variety of human EBV+ tumor-derived cells lines, only those of B-lymphoma origin that express LMP1 also secreted both CCL17 and CCL22 at high levels in vitro." (PMID 35025968, 2022). "To validate the protein expression of CCL17 and CCL17-affected immune cells in LUAD patients, we collected and examined immunohistochemical staining images and clinical information of tumor tissues from the HPA database of three LUAD patients." (PMID 35321241, 2022). "In turn, by secreting CCL5 and CCL17/TARC, HRS cells recruited T lymphocytes and then educated them to become exhausted/anergic T cells that supported tumor cell survival." (PMID 35626032, 2022). "Generally, CCL17 weakly and positively correlated with early factors of tumour grow (CXCL10), but then weakly and negatively correlated with late factors of tumour growth (myeloid cell populations); CXCL1 and CCL2 acted like CCL17 in this respect." (PMID 35226704, 2022). "The samples from TCGA-LUAD were divided into CCL17 high- and low-expression groups based on the CCL17 mRNA-FPKM expression and scored for immunity and stroma, and the immune score was considered a tangible indicator of tumor prognosis." (PMID 35321241, 2022). "In malignancy, CCR4-expressing Treg interacts with CCL17 and CCL22-secreting tumor cells, with resultant impairment of host antitumor immunity." (PMID 35464471, 2022). "A recent survey of tumor tissues from patients with GBM correlated the infiltrative character of GBM malignant cells with an increased expression of CCL15, CCL17, CD209, and TNF-α genes." (PMID 35992881, 2022). "Chemokine ligands CCL17 and CCL22 present in TME facilitate the infiltration and accumulation of Tregs in tumor tissue through chemokine receptor 4 (CCR4), a G protein-coupled receptor, primarily expressed on the most immunosuppressive Tregs population." (PMID 36613878, 2022). "The receptor CCR4 has low expression on CD8+ T cells, but its ligands CCL22 and CCL17 recruit pro-tumoural TH2 and regulatory T cells to the tumour to support tumour growth." (PMID 35205725, 2022). "We found that CCL17 and CCL22 production in different EBV+ tumor cell lines mirrored the levels of production of the EBV protein LMP1, and that the LMP1 gene on its own was sufficient to trigger chemokine expression and Treg migration into a mouse tumor model." (PMID 35025968, 2022). "M2-Mφs suppress tumor immunity and accelerate tumor progression by secreting immune suppressive factors, such as cytokines (TGF-β and IL-10) and chemokines (CCL2, CCL17, CCL22, and CCL24)." (PMID 35155237, 2022). "CCL17 and CCL22 are the ligands for CCR4, which effect on the recruitment of Treg, Th2, and Th17 into the tumor." (PMID 35517862, 2022). "We found that 47 genes were upregulated in tumor tissues compared to normal tissues, such as CD48, TIGIT, GNLY, CCL19, CCL5, CXCL13, CCL17 and NKG7." (PMID 36713530, 2022). "CCL17 and CCL22 were responsible for recruiting Treg into the tumor niche in a CCR4-dependent manner, leading to immune evasion and cancer metastasis." (PMID 36380313, 2022). "This review briefly characterizes CCR4 and its ligands (CCL17, CCL22, and CCL2), and their contributions to immunological and neoplastic diseases." (PMID 36555280, 2022).